TNF (tumor necrosis factor)
Diseases named in the same sentence as TNF in open-access papers (continued):
Sharing a sentence is not in itself a finding about the gene and the disease.
depression (continued). "Altogether, these studies indicated that TNF-α may be capable of causing mood swings and depression, and central administration of it would be an innovative method to investigate the inflammatory component of depressive disorder." (PMID 27187381, 2016). "Increased levels of proinflammatory cytokines, such as TNF-α and IL-6, have been associated with cases of depression and as per a recent study, inhibition of TNF-α prevents cognitive decline and maintains hippocampal brain-derived neurotrophic factor (BDNF) levels." (PMID 26835453, 2016). "In contrast, higher TNF-α:IL-10 was linked to a higher risk of depression among males." (PMID 27244231, 2016). "Depression is also associated with aberrant activation of inflammation, such as increases in circulating levels of interleukin (IL)-1β, IL-6, and tumor necrosis factor-α (TNFα)." (PMID 25947540, 2015). "Furthermore, the divergent effects of anti-TNF-α therapy on depressive symptoms point to the existence of potential confounders moderating the strength of the association between TNF-α and major depression." (PMID 26065825, 2015). "In patients with depression and anxiety inflammatory reaction and mild chronic inflammation were observed to be caused by increased concentration of proinflammatory cytokines like TNFα, IL-1α, IL-1β, IL-4, IL-5, IL-6, IL-12, IFNγ, and C-reactive protein." (PMID 26078821, 2015). "There are some studies indicating that depression may be associated with elevated levels of IL-1β, TNF, and IL-6." (PMID 26624891, 2015). "Clinical observations indicate that activation of the TNF-α system may contribute to the development of inflammation-associated depression." (PMID 26290874, 2015). "In addition to 5-HT signaling, elderly subjects destined to exhibit signs of major depression were more likely to harbor the GG genotype of the tumor necrosis factor (TNF)-alpha 308 (G/A) SNP variant, implicating inflammation in late-onset MD." (PMID 25133184, 2014). "Elevated levels of TNF and other inflammatory mediators and their association with anxiety or depression-like behaviors are generally studied in models of acute or chronic stress; however, TNF and TNFR1 knock out mice have been shown do display a basal “anti-depressant” phenotype." (PMID 25204558, 2014). "In addition, TNF has been implicated in depression and irritable bowel disease, recognized as migraine comorbidities." (PMID 25315199, 2014). "Finally, rs1800629, the well-known TNF -308 polymorphism, was associated with both phenotypes, supporting the previously-described influence of TNF upon depression and circadian rhythms." (PMID 23521777, 2013). "It is interesting that those peripheral cytokines that predict emergence of depression after a stroke (e.g., IL-18) differ from the key cytokines typically implicated in depressive illnesses that occur in other circumstances (e.g., IL-6, TNF-α, or IL-1β)." (PMID 23675319, 2013). "Moreover, increased IL-6 and TNFα and lower serum zinc levels are associated with risk for depression and treatment-resistant depression." (PMID 22747645, 2012). "Indeed, symptoms of depression have been positively associated with production of TNF-α by monocytes of healthy men and women." (PMID 22738397, 2012). "However, the association between TNF-α and depression remained significant even after adjusting for confounding factors in multivariate analyses." (PMID 21208443, 2011). "Furthermore, GTS-associated recovery from LPS-induced depression-like behavior was paralleled with reduced mRNA levels for IL-1β, IL-6, TNF-α, and IDO in hippocampus." (PMID 21843370, 2011). "The hypotheses of this prospective, longitudinal study were 1) patients with both cLBP and depression benefit to the same degree from the multidisciplinary pain therapy; 2) the changes of TNF-α level are associated with development of depressive symptoms." (PMID 20937108, 2010).
depression (continued). "In this article, hypotheses regarding associations of major depression, an affective disorder, and narcolepsy, a sleep disorder, with the TNF-α system are demonstrated." (PMID 19506720, 2008). "Furthermore, the dysregulation of IL-6 along with other pro-inflammatory cytokines, such as IL-1 and TNF-α, can lead to nerve inflammation, which is associated with neurodegenerative diseases such as Alzheimer’s disease (AD), Parkinson’s disease (PD), depression, and multiple sclerosis (MS)." (PMID 40305179, 2025). "Additionally, some inflammatory factors, such as interleukin-6 (IL-6) and tumor necrosis factor-alpha (TNF-α), may be associated with depression and cognitive decline." (PMID 40861349, 2025). "Therefore, IL-6, CRP, and TNF-α may represent promising targets in research on the pathomechanisms of depression and in the search for new diagnostic strategies." (PMID 40507778, 2025). "Depression, a pervasive mental health condition, has increasingly been linked to neuroinflammation, as evidenced by elevated levels of pro‐inflammatory markers such as TNF‐α and IL‐1β observed in patients, which underscores the role of inflammation in its pathophysiology." (PMID 40171943, 2025). "According to research data, in patients with somatic diseases (e.g., dermatosis) who have not previously suffered from psychiatric disorders, pro-inflammatory cytokines (including IL-1, IL-6, TNF-α) may cause true major depressive disorders (coexisting with somatic symptoms)." (PMID 40278530, 2025). "Consequently, the study indicates that the R-SNEDDS may have antidepressant effects by modulating TNF-α and interleukin pathways, presenting a promising therapeutic approach for depression associated with inflammation." (PMID 40487411, 2025). "Evidence from both adult and pediatric populations suggests that depression is linked to alterations in immune function, particularly involving pro-inflammatory cytokines such as interleukin-6 (IL-6), interleukin-1β (IL-1β), tumor necrosis factor-alpha (TNF-α), and interferon-gamma (IFN-γ)." (PMID 40563330, 2025). "This type of depression is linked to increased pro-inflammatory cytokines such as interleukin 6 (IL-6), tumor necrosis factor alpha (TNF-α), C-reactive protein (CRP), and several other factors, and these inflammatory factors may help distinguish between inflammatory and non-inflammatory depression." (PMID 38589368, 2024). "Moreover, TNF-α association with depression also seems to be verified." (PMID 37950769, 2024). "These peripheral cytokines may be implicated in depression by activating the blood-brain barrier endothelium, being transported across the blood-brain barrier into the central nervous system (CNS), (primarily TNF-α) and via circumventricular organs." (PMID 38340224, 2024). "In addition, many stress markers associated with depression such as C-reactive protein, cortisol, TNF-alpha, heart rate and systolic blood pressure can be regulated by mindfulness techniques, thus reducing negative emotional responses and increasing subjective well-being." (PMID 39424743, 2024). "Thus, the objective of this research was to understand whether homocysteine and/or the inflammatory cytokines IFN-γ, TNF-α, IL-6, and IL-1β, may be associated with depression improvement in veterans with GWI after one month on the low-glutamate diet." (PMID 39064698, 2024). "Additionally, emerging literature suggests that functional allelic variants of genes for IL-1β and TNF-α, as well as genes critical for T-cell function, may increase the risk of depression and be associated with a reduced response to antidepressant therapy." (PMID 39595067, 2024). "Analysis of the same cohort showed that elevated systemic TNF-α was associated with an increase in psychobehavioural alterations such as apathy, anxiety, depression and agitation, suggesting that increased systemic TNF-α may also have a role in hippocampal neurodegeneration." (PMID 37251808, 2023).
depression (continued). "In addition, the perinatal period itself, during which substances typically associated with high stress—e.g., TNF-α and others—may be a good marker of how significant a stressor childbirth itself might be, is regarded in this case as a trigger for depression." (PMID 37892657, 2023). "Related research shows that TNF- α is related to anxiety disorders, as it can promote the release of adrenocortical hormone through the hypothalamus pituitary adrenal axis system, thus causing neuroendocrine disorder and promoting the occurrence of anxiety and depression." (PMID 36624423, 2023). "Depression in particular may be associated with systemic inflammation and higher serum concentrations of inflammatory biomarkers such as interleukin (IL)-1 and tumor necrosis factor-alpha (TNF-a), though the nature of the association has yet to be clearly elucidated." (PMID 37754012, 2023). "Therefore, the elevation of TNF-α in brain is associated with depression." (PMID 37422634, 2023). "In addition, IL-6 and TNF-α are considered crucial systemic inflammatory factors causing chronic obstructive pulmonary disease complications such as osteoporosis, endothelial cell injury, and depression." (PMID 35892720, 2022). "Indeed, proinflammatory cytokines, including IL-1beta, interleukin-6 (IL-6), and tumor necrosis factor-alpha (TNF-alpha), have been implicated in the etiology of depression, contributing to cellular damage, impaired neuronal plasticity, and neurotransmission in the prefrontal cortex and hippocampus." (PMID 35237160, 2022). "Chronic stress-induced depression is associated with an exaggerated inflammatory response in the brain; the α7nAChR regulates the cholinergic anti-inflammatory pathway by inhibiting the synthesis/release of tumor necrosis factor-α (TNF-α) and other inflammatory cytokines." (PMID 36678660, 2022). "Furthermore, IL-6, tumor necrosis factor-alpha (TNF-α), and IL-1β are implicated in the pathophysiology of depression, and individuals with depression often have elevated circulating IL-1β, IL-6, and TNF with reduced levels of interferon-gamma (IFN-γ), IL-10, and IL-4." (PMID 35546876, 2022). "Furthermore, FMT from RA patients caused depression-like phenotypes, alterations of gut microbiota composition, increased levels of IL-6 and tumor necrosis factor-α (TNF-α), and downregulation of synaptic proteins in the PFC compared to FMT from healthy controls." (PMID 35650202, 2022). "Additionally, IL-6 and TNF-α negatively impact serotonin production and integrity, which may increase the risk of depression." (PMID 34576215, 2021). "As an inhibitor of 5-LO, emodin prevented the depression behaviors along with a series of pathological changes in the hippocampus, such as hippocampal neuron and spine loss, microglial activation, increased IL-1β and TNF-α, and the activation of 5-LO and GSK3β." (PMID 34381778, 2021). "Moreover, number of depressive episodes is associated with increased TNF-α concentrations." (PMID 33255237, 2020). "Fourth, only the level of TNF-α was increased in the hippocampus of 23-week-old Slit2-Tg mice, indicating that mild inflammation caused by overexpression of Slit2 could underlie anxiety- and depression-like behavior." (PMID 33613201, 2020). "The present finding of the effects of antidepressants on normalizing the serum TNF-α levels in patients with MDD adds to the growing body of literature that suggests that TNF-α may not only be capable of causing depression, but that it also has a role in the modulation of emotional processes." (PMID 33364982, 2020). "Therefore, targeting peripheral levels of monocyte-associated TNFα could be therapeutic in the treatment of depression." (PMID 29941796, 2018). "Moreover, individuals affected by conditions known to be associated with stress such as clinical depression anxiety, post-traumatic stress disorder, and obsessive-compulsive disorder also had elevated concentrations of TNF-alpha in blood." (PMID 30510499, 2018).
depression (continued). "However, an elevated TNF‐α level has been somewhat associated with severe forms of depression." (PMID 29670819, 2018). "Indeed, we found that higher levels of maternal TNF-α were associated with lower risk of adult depression in analyses of males and females combined, suggesting that some aspects of the neurodevelopmental effects of maternal HPA-immune activity do not vary between males and females." (PMID 27244231, 2016). "The sex difference in the association between maternal immune activity and offspring's risk of depression was because of sex-dependent variation in TNF-α relative to IL-10, and, therefore, we speculate the inability of the mother to mount an anti-inflammatory (IL-10) response to adverse stimuli." (PMID 27244231, 2016). "Functional polymorphisms within pro-inflammatory cytokine genes such as Interleukin-1beta (IL-1beta) and tumor necrosis factor-alpha (TNF-alpha) may increase the risk of depression and are associated with reduced responsiveness to conventional antidepressant therapy." (PMID 23416033, 2013). "A cancer diagnosis itself may lead to posttraumatic stress disorder (PTSD), causing depression and anxiety as well as an increased level of biomarker expression, such as interleukin-6 (IL-6), tumor necrosis factor-α (TNF-α), cortisol, and high-reactive sensitive C-reactive protein." (PMID 24285975, 2013). "Interestingly, present data also demonstrated that the level of IL-6 and TNF-á was positively correlated with the depressive behavior, supporting the hypothesis that the inflammatory cytokines cause development of depression." (PMID 22860054, 2012). "Our hypothesis was that patients with both cLBP and depression display higher TNFα serum levels than patients with cLBP alone and there are cross-sectional associations of pain, depressive symptoms and their interaction with TNFα in cLBP." (PMID 20937109, 2010). "A large-scale meta-analysis indicated that levels of TNF-α, IL-6, IL-1RA are elevated in patients with depression, while IFN-γ levels tend to decrease." (PMID 41601490, 2026). "The results showed that the mRNA levels of IL‐1β, iNOS, IL‐6, and TNF‐α were increased in the brain of depression model mice, and all of them were down‐regulated in the DSCG‐treated depression model mice." (PMID 41556446, 2026). "A previous meta‐analysis has shown that increased microglial activity induces increased levels of TNF, interleukin‐8 (IL‐8), and IL‐6 in cerebrospinal fluid (CSF) and brain tissue of patients with depression." (PMID 40202374, 2025). "Wendan decoction effectively reduced the levels of pro-inflammatory factors IL-1β, IL-6, and TNF-α, with similar anti-inflammatory effects reported in depression treatment, underscoring its multimodal therapeutic action." (PMID 40713709, 2025). "Our study found that participants with severe depressive symptoms had significantly higher concentrations of CRP, IL-6, and TNF-α, reaffirming a robust link between inflammation and depression." (PMID 40363978, 2025). "TNF-α levels have been found to be positively correlated with major depressive disorder (MDD) severity in serum and have a predictive value." (PMID 40077572, 2025). "In rodent models of depression induced by chronic unpredictable stress, expressions of TNF, IL-1β, IL-6, cyclooxygenase-2 (COX-2), and inducible nitric oxide synthase (iNOS) are elevated in the hippocampus." (PMID 40710585, 2025). "Crucially, there is a lack of robust clinical evidence demonstrating that modulation of depression or direct TNF-α inhibition significantly improves survival outcomes in cancer patients." (PMID 41000397, 2025). "The other cytokines measured—IL-1β, IL-4, IL-10, and TNF-α—showed little variation throughout the different phases, indicating their minimal involvement in the mediation of depression." (PMID 40564108, 2025). "Pro-inflammatory cytokine levels, including TNF-α, IL-6, and IL-1β, are continuously elevated in patients with AD, MS, and depression." (PMID 39861166, 2025).
depression (continued). "Carvacrol, a monoterpene found in the essential oils of aromatic plants such as Origanum vulgaris and Thymus vulgaris, reduces oxidative stress and decreases hippocampal IL-1β and TNF-α levels, thereby improving depression-like behavior induced by CUMS." (PMID 40936908, 2025). "For depression, TNF-α interferes with serotonin and dopamine systems by altering how synapses function and reducing levels of brain-derived neurotrophic factor (BDNF), a protein essential for maintaining healthy neurons and stable mood." (PMID 40941042, 2025). "In a randomized controlled trial, the cytokine TNFα antagonist infliximab was administered to medically stable outpatients with major depression." (PMID 40352929, 2025). "In patients with cancer as well as depression and fatigue, there are also elevated circulating inflammatory cytokines, and peripheral blood interleukin (IL)-1β, IL-6, tumor necrosis factor, and CRP levels show an increasing trend." (PMID 40966684, 2025). "Cognitive test results and anxiety and depression at baseline and after 6 months of treatment with TNF inhibitors." (PMID 40291023, 2025). "A growing amount of data indicates that the overproduction of pro-inflammatory cytokines, such as IL-1β, IL-6, and TNF-α, by immune cells within the brain, plays an important role in the onset and progression of depression." (PMID 40612748, 2025). "•Meta-analysis showed association between TNF-a, IFN-g, IL-6 and IL-10 and depression in individuals with MS." (PMID 39867847, 2025). "This miRNA was also indicated by a subsequent investigation to be upregulated in the blood of patients with major depressive disorder where, in addition, its expression positively correlated with TNF-α concentrations." (PMID 40806453, 2025). "Several studies have reported elevated levels of proinflammatory cytokines, CRP and TNF-a among patients suffering from major depressive disorders." (PMID 40003621, 2025). "In summary, biologics targeting inflammatory pathways such as those mediated by IL - 6, TNF-α, and IL - 1 exhibit considerable potential for intervening in depression and cancer comorbidity." (PMID 41000397, 2025). "Lastly, for every unit increase (pg/dL) in TNF- α, the odds of clinical depression rose approximately 2.5 times or by 150%." (PMID 39902492, 2025). "IL‐18 positively correlated with AUDIT, ADS, OCDS, BSA and anxiety/depression measures, and TNF‐α positively correlated with ADS, AUDIT and STAI‐T." (PMID 40317574, 2025). "Previous research has also shown that some anti-inflammatory therapies, including TNF inhibitors, reduce symptoms of depression in patients with an inflammatory disease." (PMID 39504461, 2025). "Small trials of cytokine inhibitors (e.g., anti-TNF agents or IL-6 blockers) in treatment-resistant depression have shown modest benefits." (PMID 41149069, 2025). "Next, we examined social and depression-like phenotype and the expression of pro-inflammatory markers (TNF-α, IL-1β, NF-κB1, and IL-6) in the ventromedial prefrontal cortex (vmPFC) and hippocampal CA1 brain regions." (PMID 40558565, 2025). "Microglial activation and the subsequent release of inflammatory factors (TNF-α and IL-6) are key contributors to anxiety and depression-like phenotypes." (PMID 41465379, 2025). "Elevated levels of pro-inflammatory cytokines, such as interleukin-6 (IL-6) and tumor necrosis factor-alpha (TNF-α), have been associated with impaired cognitive control and increased risk of depression and anxiety." (PMID 40062198, 2025). "Recent studies have shown that peripheral immune-to-brain signaling can disrupt neural homeostasis via cytokines such as IL-6 and TNF-α and lead to depression." (PMID 41425563, 2025). "Previous studies have reported that microglia in the brains of depression patients exhibit abnormal activation, with significantly elevated expression levels of pro-inflammatory cytokines IL-1β, IL-6, and TNF-α." (PMID 41244868, 2025).